PDCD4 (programmed cell death 4)
Diseases named in the same sentence as PDCD4 in open-access papers (continued):
Sharing a sentence is not in itself a finding about the gene and the disease.
bacterial infections (1 paper, 2024). "The effectiveness of the TOSI reporter in drug screening underscores the importance of inhibitors that restrict mycobacterial growth, thereby underlining the growing relevance of PDCD4 in bacterial infections and indicating promising avenues for future therapeutic developments." (PMID 38912807, 2024).
hematological malignancies (1 paper, 2020). "Further potential targets of miR-21 were detected like AP-1 and programmed cell death protein 4 (PDCD4) in solid and hematological malignancies." (PMID 31973111, 2020).
infectious disease (1 paper, 2024). A disorder directly resulting from the presence and activity of a microbial, viral, or parasitic agent in humans. "Our insights also pave the way to explore PDCD4’s role beyond oncological contexts, potentially emphasizing its pertinence in mycobacterial-induced infectious diseases." (PMID 38912807, 2024).
PDCD4 also shares sentences with these, for which no sentence is quoted: adenocarcinoma (3 papers); chronic lymphocytic leukaemia (3); acute kidney injury (2); acute myocardial infarction (2); adenoma (2); gynecologic cancers (2); metabolic syndrome (2); metastatic colorectal cancer (2); metastatic disease (2); Osteopenia (2); pulmonary hypertension (2); age (1); allergic asthma (1); bipolar disorder (1); bone metastasis (1); carcinoma in situ (1); cerebral tumors (1); cervical intraepithelial neoplasia (1); chronic multifocal osteomyelitis (1); chronic pancreatitis (1); colonic adenomas (1); coronary artery stenosis (1); COVID-19 (1); diffuse large B-cell lymphoma (1); digestive system cancer (1); digestive system tumors (1); ductal carcinoma in situ (1); endometriosis (1); epilepsy (1); Ewing sarcoma (1).
A further 41 diseases each share a sentence with PDCD4 in 1 paper.